MASP1 (MBL associated serine protease 1)
Diseases named in the same sentence as MASP1 in open-access papers (continued):
Sharing a sentence is not in itself a finding about the gene and the disease.
pertussis (1 paper, 2025). A contagious bacterial respiratory infection caused by Bordetella pertussis. "Furthermore, through the application of machine learning algorithms, this study successfully identified the key gene MASP1 associated with pertussis." (PMID 39841046, 2025). "By integrating multi-omics analysis and experimental validation, this study elucidated the pivotal role of MASP1 in severe pertussis among children, substantiating the potential of inhibiting MASP1 expression to significantly alleviate pertussis symptoms." (PMID 39841046, 2025). "The study highlights the critical role of MASP1 in pertussis, providing a crucial foundation for developing therapeutic strategies targeting MASP1." (PMID 39841046, 2025). "This study utilized multi-omics analysis to uncover the crucial role of MASP1 in severe pertussis in children." (PMID 39841046, 2025). "Through machine learning algorithms and protein–protein interaction (PPI) network analysis, this study identified MASP1 as a characteristic gene of pertussis, revealing its significantly upregulated expression in pertussis patients." (PMID 39841046, 2025). "The main objective of this study is to investigate the role of the MASP1 protein in severe pertussis in children through multi-omics analysis, with the aim of providing a theoretical basis for the development of novel therapeutic strategies for this disease." (PMID 39841046, 2025). "The results demonstrated that MASP1 overexpression exacerbated pertussis-induced cell damage, adding to the understanding of MASP1’s involvement in cellular inflammatory responses from previous studies." (PMID 39841046, 2025). "This study, for the first time, employed a combination of multi-omics and machine learning methods to screen and validate MASP1 as a characteristic gene with expression changes in pertussis." (PMID 39841046, 2025). "Future research should aim to expand the sample size, encompassing pertussis patients of different age groups and varying severity of the disease, to validate the universality and efficacy of targeting MASP1 as a treatment approach." (PMID 39841046, 2025). "Particularly, the significant upregulation of MASP1 in severe pertussis patients suggests its potentially important role in disease progression, offering a foundation for further exploration of MASP1’s universal mechanisms in infectious diseases." (PMID 39841046, 2025). "Second, although both in vitro and in vivo experiments suggest that inhibiting MASP1 can help alleviate pertussis symptoms, more clinical trials are needed to confirm the applicability of these results to humans." (PMID 39841046, 2025). "This study aims to investigate the role of the MASP1 protein in severe pertussis in children through multi-omics analysis, providing a theoretical basis for the development of novel therapeutic strategies." (PMID 39841046, 2025). "While past research primarily focused on the role of MASP1 in other infectious diseases, this study uncovered, for the first time in the context of pertussis, the crucial regulatory role of MASP1." (PMID 39841046, 2025). "Specifically, interventions targeting MASP1 present a promising avenue for treating severe pertussis, potentially lowering the complications and mortality associated with infections, thereby enhancing patients’ quality of life." (PMID 39841046, 2025). "The results revealed significant differences in microbial diversity and specific flora abundance between healthy children and those with pertussis, with MASP1 significantly upregulated in severe pertussis and its inhibition alleviating infection symptoms." (PMID 39841046, 2025). "Subsequently, through protein–protein interaction network analysis and machine learning algorithms, the study screened and validated the expression changes of the characteristic pertussis gene MASP1, revealing its crucial role in the process of pertussis infection." (PMID 39841046, 2025).
pertussis (continued). "To investigate the relationship between MASP1 and the severity of pertussis, we used the human airway epithelial cell line HBE135-E6E7 (E6E7) to establish a B. pertussis infection model, as described in the Methods section, and measured intracellular cAMP levels." (PMID 39841046, 2025). "Subsequently, the expression changes of MASP1 were validated on the HBE135-E6E7 human bronchial epithelial cell line in vitro, and the relationship between MASP1 and pertussis-induced airway epithelial cell damage was investigated by constructing MASP1-overexpressing and knockdown cell lines." (PMID 39841046, 2025). "Finally, while this study has uncovered the critical role of MASP1 in pertussis, further research is required to delve into its specific molecular mechanisms and regulatory pathways." (PMID 39841046, 2025). "In summary, our screening has identified MASP1 as a characteristic gene of pertussis." (PMID 39841046, 2025). "Additionally, in-depth exploration of the specific molecular mechanisms and signaling pathways of MASP1 in the pathogenesis of pertussis can lead to the discovery of more potential therapeutic targets, refining existing treatment approaches." (PMID 39841046, 2025). "This discovery not only enhances the understanding of pertussis pathogenesis but also provides a novel perspective for the academic community and lays a solid theoretical foundation for the development of therapeutic strategies targeting MASP1 in clinical settings." (PMID 39841046, 2025). "However, the specific function and regulatory mechanisms of MASP1 in pertussis remain unclear." (PMID 39841046, 2025). "A Bordetella pertussis infection model was established using human bronchial epithelial cell line HBE135-E6E7 to validate MASP1 expression changes and investigate its relationship with airway epithelial cell damage by constructing cell lines overexpressing and knocking down MASP1." (PMID 39841046, 2025).
Pleural effusion (1 paper, 2023). The presence of an excessive amount of fluid in the pleural cavity. "One patient with severe CLS and TMA/VOD with rapid weight gain, ascites, pleural effusion, elevated bilirubin, hepatomegaly, low levels of coagulation factors and GI-bleeding, had an ultrarare missense variant in the MASP1 gene (rs1712360640; Ala544Thr)." (PMID 37771589, 2023).
pulmonary tuberculosis (1 paper, 2018). A bacterial infection that affects the lungs and is caused by Mycobacterium tuberculosis. "In conclusion, our results demonstrate a significant association of MASP1 polymorphism rs3774275 and MASP1 serum levels with the development of pulmonary TB." (PMID 29515573, 2018). "In this study, we identified an intronic SNP in the MBL-associated serine protease (MASP1) gene, an important component of the lectin pathway of the complement, associated with pulmonary tuberculosis (PTB) infection in our population." (PMID 29515573, 2018). "Our study is now the first study to demonstrate an association between MASP1 serum levels and pulmonary TB." (PMID 29515573, 2018).
respiratory infections (1 paper, 2025). "Prior studies have indicated that MASP1 plays a role in exacerbating respiratory infections." (PMID 39841046, 2025).
thrombotic microangiopathy (1 paper, 2025). The syndromes of microangiopathic hemolytic anemia, thrombocytopenia, and variable signs of organ impairment, due to platelet aggregation in the microcirculation. "Patients with LN with thrombotic microangiopathy have stronger staining intensity and deposition of MBL, MASP1/3, CFB, CFD, C4d, and VWF." (PMID 41031884, 2025).
tubulointerstitial nephritis (1 paper, 2018). "One possible reason is that, similar to the wild-type MRL/lpr mice, the Masp1/3−/− MRL/lpr mice developed tubulointerstitial nephritis." (PMID 29892304, 2018).
vasculitis (1 paper, 2023). "Overall, the high fold increases in MASP1 and CFB together with decreased SERPINA5 and increased C9 suggest the role of the lectin and alternate complement pathway in this form of vasculitis." (PMID 37238213, 2023).
ZIKV infection (1 paper, 2023). "The lack of induction of MASP1 and MASP2 suggests that the lectin pathway is not induced and that this increase in C2 and C4a reflects an increase in the classical pathway by ZIKV infection." (PMID 37022660, 2023).
infection (18 papers, 2011 to 2025). The state of being infected such as from the introduction of a foreign agent such as serum, vaccine, antigenic substance or organism. "Further studies with controls classified for asymptomatic infection will help to clarify the type of protection that is associated with the MASP1 variant rs3774275." (PMID 29515573, 2018). "In conclusion, the characteristic “double-edge” association of MASP-2 (and probably also of MASP-1 and other LP components) with immunosuppression, infection and inflammation poises a difficult question regarding therapies directed to its inhibition, motivating further investigations in this field." (PMID 33729332, 2021). "In recent years, an increasing number of studies have identified various expression patterns of MASP1 in infectious diseases, suggesting its potential key role in pathogen infection processes." (PMID 39841046, 2025). "Lentiviral vectors were used to suppress MASP1 expression in lung and airway tissues, and relevant indicators were measured post-infection." (PMID 39841046, 2025). "Further investigation indicated an upregulation of MASP1 expression in airway epithelial cells post-infection." (PMID 39841046, 2025). "Using a mouse model of pertussis infection, this study evaluated the impact of inhibiting MASP1 expression on infection symptoms." (PMID 39841046, 2025). "The activation of MASP-1 during wound-healing processes can be a part of a normal tissue repair process (activated by damaged/altered host cells) or a result of an infection." (PMID 38612857, 2024). "MASP-1, an alternative splice variant of the MASP-1/3 gene, was unaffected by infection with either control or shMASP-3 RNA lentiviruses." (PMID 30417171, 2018). "The lectin pathway of the complement system activates after infection and oxidative stress on endothelial cells generating active serine proteases: MASP-1 and MASP-2." (PMID 21625439, 2011). "Finally, the impact of inhibiting MASP1 expression on infection symptoms was evaluated using a mouse pertussis infection model." (PMID 39841046, 2025). "Finally, the impact of inhibiting MASP1 on infection symptoms was evaluated using a mouse model of pertussis infection." (PMID 39841046, 2025). "Moreover, MASP levels (MASP-1, MASP-2, and MASP-3) were shown as a predictor for infection and prolonged dependency of intensive care in critically ill children." (PMID 25654073, 2014). "On the other hand special activation of MASP-1 occurring during infection, oxidative stress or possibly other conditions may initiate HAE attacks." (PMID 21625439, 2011). "However, in chronic or prolonged inflammation, the lectin pathway may already be activated, and a secondary infection may result in newly synthesized or incoming activators (pretreatment with MASP-1)." (PMID 37298134, 2023). "Transepithelial electrical resistance (TEER), an important indicator of epithelial function, was measured, and results showed that after 12 and 24 h of infection, TEER was significantly decreased in the oe-MASP1 + Control group compared with the control group (oe-NC + Control)." (PMID 39841046, 2025). "MASP-1 and MASP-2 can be activated during infection or stressful conditions." (PMID 21625439, 2011).
tumor (12 papers, 2013 to 2026). "A six-gene risk score, the SCCHN TMI (SCCHN-tumor matrisome index: composed of MASP1, EGFL6, SFRP5, SPP1, MMP8 and P4HA1) was constructed and used to stratify patients into risk groups." (PMID 34830910, 2021). "The evidence to date suggests that MASP1 may be involved in reprogramming of lipid metabolism with consequent effects on various immunological and genomic factors, in the tumor immune microenvironment." (PMID 41439026, 2025). "Patients with higher serum MASP-1 levels may have exacerbated complement activation, which leads to basement membrane disorder and eventually to basement membrane injury or rupture, resulting in tumor invasion." (PMID 37519786, 2023). "High levels of MASP-2 and MASP-1 may increase activation of the complement system by the lectin pathway, thereby augmenting the release of C5a, a potent anaphylatoxin that activates cellular responses involved in tumor growth and progression." (PMID 30532757, 2018). "The single-cell RNA-seq analysis of the SCCHN TMI genes revealed that four of these genes (MASP1, EGFL6, SPP1, and P4HA1) are expressed in subpopulations of fibroblasts, macrophages, T cells and in tumor cells." (PMID 34830910, 2021). "It is possible that patients with higher serum levels of MASP-1 and/or MASP-2 present exacerbate activation of complement leading to the disturbance of the basement membrane, and ultimately to its damage or rupture and consequently, tumor invasion." (PMID 30532757, 2018).
cancer (8 papers, 2013 to 2025). A tumor composed of atypical neoplastic, often pleomorphic cells that invade other tissues. "Conversely, mannan-binding lectin (MBL)-associated serine protease (MASP)-1, MASP-3, collectin liver-1 (CL-L1), and MBL-associated protein of 44 kilodalton (MAp44) levels were decreased in cancer patients compared with healthy individuals (all P ≤ 0.04)." (PMID 32267878, 2020). "The mutation in MASP1 may cause cancer because of immunological abnormality." (PMID 36793597, 2023). "Among them, 8 of 12 hub genes (EPHX3, SPINK7, FCRLA, MASP1, ZNF541, CD5, BEST2, ZAP70) seemed to be cancer-promoting genes as they were downregulated in the high-risk group." (PMID 35846149, 2022). "Contrary to this, MASP-1, MASP-3, CL-L1, and MAp44 concentrations were significantly lower in cancer patients than in healthy individuals (all P-values ≤ 0.04)." (PMID 32267878, 2020). "In our study, MASP-1 serum concentrations were significantly higher in cancer patients than in other studied groups." (PMID 30532757, 2018). "Overexpression of MASP1 through lentiviral transfection in HCC cell lines was shown to inhibit the proliferation, migration, and invasion of the cancer cells in in vitro cell culture assays and in vivo as xenografts in nude mice, thus establishing MASP1 as a tumor suppressor protein." (PMID 41439026, 2025). "Reduced perioperative levels of MBL, M-ficolin, MASP-1, MASP-3, MAp44, and MASP-2 have previously been found in cancer patients undergoing laparoscopic colectomy." (PMID 32267878, 2020). "M-ficolin and H-ficolin were found in higher concentrations in cancer patients than in healthy individuals, while CL-L1, MASP-1, MASP-3, and MAp44 were found in lower concentrations in cancer patients than in healthy individuals." (PMID 32267878, 2020). "MASP-1, MASP-2, MASP-3, MAp-44, and MAp-19 serum concentrations in patients with cervical lesions and cancer." (PMID 30532757, 2018).
infectious disease (5 papers, 2016 to 2025). A disorder directly resulting from the presence and activity of a microbial, viral, or parasitic agent in humans. "Genetic mutations resulting in human MASP1 deficiency are associated with infectious disease, and several intronic mutations leading to MASP1 deficiency have been identified, though none are identical to the associations found here." (PMID 29744529, 2018). "Nevertheless, MASP1 has not yet been studied in association to many infectious diseases." (PMID 29515573, 2018).
bacterial infections (3 papers, 2018 to 2023). "In particular, we found considerable types of cooperation between MASP-1 and LPS, highlighting the risks of bacterial infections under conditions where the complement system was already activated or could be easily triggered." (PMID 37298134, 2023). "In case of a bacterial infection, the LP can be activated, and the resulting active MASP-1 and MASP-2 molecules could locally convert pro-FD to FD, making the AP amplification possible." (PMID 30135690, 2018).
renal disease (3 papers, 2014 to 2022). "MASP-1/3-deficient mice were shown to lack lectin and alternative pathway activation, but mice with the combined deficiencies of factor H, MASP-1 and MASP-3 showed uncontrolled complement activation and developed complement-mediated renal disease." (PMID 35677590, 2022). "The implication is that inhibition of MASP-1 is not a viable strategy to treat renal disease associated with uncontrolled AP activation." (PMID 24279761, 2014).
blood cancers (1 paper, 2023). "Expanding the protein-protein interaction analysis for blood cancers revealed an additional network consisting of CD46, CFP, MASP1 and SERPINE1, correlated with short overall survival." (PMID 36649303, 2023).
malformation syndrome (1 paper, 2024). "Masp1 has been reported to encode mannan-binding lectin serine protease 1, and its mutations are linked to a human malformation syndrome." (PMID 39857604, 2024).
metabolic disorders (1 paper, 2023). "In addition to these genes, variants were found in seven genes (ALDOB, MASP1, KIAA1109, TRAPPC4, SMARCAL1, HERC1, RRAS2) that were previously not reported in MPS but associated with other metabolic disorders." (PMID 37091798, 2023).
MASP1 also shares sentences with these, for which no sentence is quoted: 3MC syndrome 1 (3 papers); colorectal cancer (3); coronary artery disease (3); Intellectual disability (3); acute myocardial infarction (2); arterial hypertension (2); cardiovascular disease (2); colon carcinoma (2); craniosynostosis (2); endothelial dysfunction (2); growth deficiency (2); head and neck cancer (2); hearing loss (2); Hepatitis (2); lupus nephritis (2); melanoma (2); pneumococcal meningitis (2); preeclampsia (2); renal failure (2); systemic inflammatory response syndrome (2); viral infection (2); acute respiratory distress syndrome (1); age-related maculopathy (1); allergic asthma (1); Alzheimer disease (1); attention deficit-hyperactivity disorder (1); autoimmune disease (1); autoimmune thyroiditis (1); bacterial sepsis (1); benign ovarian tumours (1).
A further 48 diseases each share a sentence with MASP1 in 1 paper.